DNASE1L2 (deoxyribonuclease 1 like 2)
Description:
Divalent cation-dependent acid DNA endonuclease involved in the breakdown of the nucleus during corneocyte formation of epidermal keratinocytes. May play an immune role by eliminating harmful DNA released into the extracellular environment by damaged epidermal cells.
Synonyms: DNAS1L2
Tractability: Antibody: UniProt places it where antibodies can reach, with high confidence; UniProt predicts a signal peptide or a membrane-spanning region; its Gene Ontology location is reachable by antibodies, with medium confidence.
Gene: Protein-coding gene on chromosome 16 (2,235,816 to 2,238,711, forward strand). Ensembl gene ENSG00000167968.
Subcellular location: Cytoplasm; Secreted
Subcellular location (Human Protein Atlas): Mitochondria; Predicted to be secreted
Gene Ontology:
Molecular function: protein binding; calcium ion binding; deoxyribonuclease I activity; DNA binding; DNA nuclease activity; catalytic activity
Biological process: DNA catabolic process; DNA metabolic process
Cellular component: nucleus; cytoplasm; extracellular region
Genetic constraint (gnomAD): Loss-of-function variants: 35 observed, 26.31 expected, observed/expected ratio (o/e) 1.33, 90% interval 1.01 to 1.75. The synonymous counts are far from expectation, so gnomAD's model fits this gene poorly and the ratio says little. Missense variants: 504 observed, 391.19 expected, observed/expected ratio (o/e) 1.29, 90% interval 1.2 to 1.39. Synonymous variants: 211 observed, 166.35 expected, observed/expected ratio (o/e) 1.27, 90% interval 1.13 to 1.42.
Homologues: Orthologues: chimpanzee DNASE1L2 (99% identical), macaque DNASE1L2 (90% identical), dog DNASE1L2 (82% identical), rabbit DNASE1L2 (78% identical), pig DNASE1L2 (78% identical), mouse Dnase1l2 (77% identical), rat Dnase1l2 (77% identical), guinea pig DNASE1L2 (76% identical), tropical clawed frog dnase1l2 (53% identical), zebrafish dnase1 (47% identical). Paralogues in human: DNASE1 (51% identical), DNASE1L3 (41% identical), DNASE1L1 (37% identical).
Diseases named in the same sentence as DNASE1L2 in open-access papers:
DNASE1L2 is named in the same sentence as 10 diseases in open-access papers, as found by Europe PMC text mining. Sharing a sentence is not in itself a finding about the gene and the disease. The quoted sentences say what the papers report.
psoriasis (3 papers, 2017 to 2021). An autoimmune condition characterized by red, well-delineated plaques with silvery scales that are usually on the extensor surfaces and scalp. "Observations in humans however show that SNPs in DNASE1L2 are associated with psoriasis and that DNASE1L2 expression is reduced in the inflamed psoriatic skin." (PMID 33717156, 2021). "In normal epidermis, a set of endonucleases, in particular DNase1L2 and APE1, are active, but this enzymatic activity is altered in psoriasis." (PMID 28095445, 2017).
breast carcinoma (1 paper, 2023). "In breast cancer, DNASE1L2 influenced the growth and metastasis of cancer cells by modulating the epithelial–mesenchymal transformation process." (PMID 37745305, 2023).
cancer (4 papers, 2015 to 2023). A tumor composed of atypical neoplastic, often pleomorphic cells that invade other tissues. "The cancer related category apoptosis was over-represented with both up- and down-regulated genes, represented by two up-regulated genes (TNS3, EMP1) and five genes down-regulated (DNASE1L2, CXCR4, Gal-7, FKBP5, SGK1)." (PMID 25867603, 2015).
tumor (2 papers, 2020 to 2023). "The results revealed that expression levels of SLCO4C1, POU4F1, DNASE1L2, WDR72, LPO, and C7 in tumor tissues were significantly higher than those in normal tissues, while the expression differences of SLC4A4, CELF4, and SLC11A1 were not statistically significant." (PMID 37745305, 2023).
bacterial infection (1 paper, 2025). "This suggests that DNASE1L2 may play a critical role in regulating the immune response by participating in DNA destruction during bacterial infection-induced inflammation." (PMID 40428293, 2025).
DNASE1L2 also shares sentences with these, for which no sentence is quoted: autoimmune disease (1 paper); colorectal cancer (1); COVID-19 (1); kidney disease (1); Sepsis (1).